TNF (tumor necrosis factor)
Diseases named in the same sentence as TNF in open-access papers (continued):
Sharing a sentence is not in itself a finding about the gene and the disease.
hypogonadism (14 papers, 2018 to 2025). A disorder characterized by decreased function of the gonads. "In brief, in an animal model of hypogonadism, reduced testosterone levels were associated to elevated inflammatory cytokines such as IL-6, IL-1β, and TNF-α." (PMID 37298172, 2023). "Our findings showed a significant and inverse connection between TNF-α and inhibin B and these findings are consistent with a previous study that reported hypogonadism to be associated with inflammatory markers." (PMID 36381078, 2022). "We found that male castration increased the recruitment of inflammatory cells and upregulated the expression of TNF-α and IL-6, similar to clinical reports that higher levels of IL-6, IL-1β, and TNF-α were noted in men with testosterone deficiency (hypogonadism)." (PMID 33475136, 2021). "Of note, animal and human studies have reported that hypogonadism is linked with pro-inflammatory cytokines which may adversely affect erectile function mainly in aging men because testosterone blocks a variety of cytokines, including TNF-α, IL-1β, and IL-649." (PMID 37045862, 2023). "Multiple factors contribute to secondary hypogonadism, including inflammatory mediators of low chronic inflammation, such as tumor necrosis factor and interleukin 1; insulin resistance; leptin resistance; and reduced kisspeptin secretion." (PMID 37479795, 2023). "One common observation in these studies is that higher levels of IL-6, IL-1β, TNF-α, and CRP were noted in men with testosterone deficiency (hypogonadism)." (PMID 30558178, 2018). "Indeed, hypogonadism increases inflammatory markers (TNFα and IL‐6)." (PMID 33794059, 2021). "The level of TNF-α is higher in adult men with lower testosterone levels, while the expression of TNF-α is inhibited by testosterone in men with hypogonadism." (PMID 39199439, 2024). "It has been found that the level of TNF-α is higher in adult men with lower testosterone levels, while the expression of TNF-α is inhibited by testosterone in men with hypogonadism." (PMID 34526062, 2021).
hypoxic-ischemic encephalopathy (14 papers, 2014 to 2025). "Prolonged sleep deprivation also induces inflammatory activation—elevated TNF-α and C-reactive protein have been observed in women with perinatal depression, particularly among those with trauma histories." (PMID 41561847, 2025). "Further investigation of IL-8 and CRP in relation to treatment response, along with replication of TNF-α findings, is warranted to advance perinatal depression research." (PMID 41440970, 2025). "A pilot study reported an inverse connection between IL-1β, TNF-α, and IL-17 and perinatal depression." (PMID 37239199, 2023). "Our results confirmed that neonatal hypoxia-ischemia markedly decreased the methylation level at CpG islands 1-7 in the TNF-α promoter region, which is a critical proinflammatory factor in neonatal hypoxic-ischemic encephalopathy." (PMID 33488693, 2020). "TNF-α is a key proinflammatory cytokine in neonatal hypoxic-ischemic encephalopathy and prevents nerve growth and repair." (PMID 33488693, 2020). "A relationship between serum levels of IL-1β, IL-6, and TNF-α and the outcome of infants that have suffered of perinatal asphyxia has been observed in humans, suggesting that proinflammatory cytokines have a predictive value." (PMID 24723845, 2014). "TNF-α and IL-1β showed prolonged, higher expression levels than the controls, suggesting that the LPS/Hypoxia animals are experiencing a longer inflammatory state similar to that seen in human preterm hypoxic-ischemic encephalopathy." (PMID 40810121, 2025). "Indeed, a study of blood and CSF obtained during the first 24 h of life from infants who suffered hypoxic ischemic encephalopathy showed an increase in IL-1β, IL-6, and TNF-α levels, compared to control infants." (PMID 24723845, 2014). "Elevated TNF-α and acute-phase protein levels were observed in patients with perinatal depression and those exposed to trauma, suggesting that chronic stress and attachment insecurity may synergistically exacerbate depressive vulnerability through inflammatory pathways." (PMID 41561847, 2025). "Following hypoxic ischemic encephalopathy, ICV injection of human umbilical cord-derived MSCs could exhibit neuroprotective effects via suppressing apoptosis and regulating the secretion of TNF-α and IL-1β." (PMID 37605722, 2023). "However, the mechanism by which Chinese Tuina improved the inflammatory response in neonatal hypoxic-ischemic encephalopathy was independent of the regulation of methylation levels in IL-10 and TNF-α." (PMID 33488693, 2020). "The present study aimed to investigate the potential roles of interleukin-6 (IL-6), tumor necrosis factor-α (TNF-α) and high-sensitivity C-reactive protein (Hs-CRP) in the progression and prognosis of neonatal hypoxic-ischemic encephalopathy (HIE)." (PMID 25187835, 2014).
kidney cancer (14 papers, 2016 to 2026). Primary or metastatic malignant neoplasm involving the kidney. "A decreased level of the oncogenic miRNA-381-3p, which is a dual suppressor of TNF-induced apoptosis and necroptosis that promotes the proliferation of kidney cancer cells, was observed." (PMID 41303298, 2025). "One of the plausible mechanisms linking albuminuria to kidney cancer was the tumor microenvironment orchestrated via inflammatory parameters, namely, TNF‐α or hs‐CRP, which could foster proliferation, survival, and migration of kidney cancer cells." (PMID 36069056, 2023). "However, with the progression of ccRCC, the communication intensity gradually decreases, which indicates that TNF signal communication in the immune microenvironment of ccRCC could effectively inhibit the progression of kidney cancer." (PMID 34804944, 2021). "Here, we found that, in HEK293 kidney cancer cells, TGR5-transfected cells with the ligand treatment suppressed gene expression of IL-1α, IL-1β, IP-10, and MCP-1 induced by TNF-α or p65 overexpression." (PMID 28903349, 2017).
kidney stones (14 papers, 2014 to 2026). "There have been no reports in the literature stating that immunosuppressants, methotrexate, or anti-tumor necrosis factor agents contribute to the formation of renal calculi in any way." (PMID 40332308, 2025). "In this study, Hyp intervention exhibited a notable decrease in the levels of IL-1β, IL-6, IL-8, and TNF-α in cell and rat models, suggesting the anti-inflammatory role of Hyp in nephrolithiasis." (PMID 36942317, 2023). "Given the importance of renal immune response in the pathophysiology of kidney stones, we investigated the correlations between miR-155 and important proinflammatory cytokines: IL-1β, IL-6, and TNF-α, a chemokine (RANTES) in the urine sediment." (PMID 25197634, 2014). "Natural active ingredients prevent and treat kidney stones by modulating inflammatory and oxidative stress related pathways, the mechanism of which involves inhibition of the release of pro-inflammatory factors such as IL-1β, IL-6, TNF-α etc." (PMID 41019076, 2025). "The results showed that TGF-Β1, TNFα, and MCP-1 transcription levels increased significantly in rat kidney tissue from the nephrolithiasis group, while yellow tea gavage significantly inhibited these levels in a dose-dependent manner." (PMID 37569334, 2023). "Repressing the release of pro-inflammatory cytokines, such as IL-1β, TNF-α, IL-6, and oxidative stress mediators, such as ROS, and MDA, can markedly relieve pain and cell apoptosis in kidney stones." (PMID 38154105, 2023). "We first confirmed PPAR expression changes including upregulation PPARG, TGF-β1, TNF-α, and MCP-1 expression in ethylene glycol-induced nephrolithiasis rats by RT-qPCR, immunofluorescence staining, and Western blot analyses." (PMID 37569334, 2023). "For clarifying the effects of Hyp on oxidative stress injury and inflammatory response in rats with renal calculi, we measured the levels of oxidative stress-related substances (MDA, LDH, ROS, and SOD) and inflammatory factors (IL-1β, IL-6, IL-8, and TNF-α) in the kidney tissue of rats." (PMID 36942317, 2023).
leiomyoma (14 papers, 2007 to 2026). A well-circumscribed benign smooth muscle neoplasm characterized by the presence of spindle cells with cigar-shaped nuclei, interlacing fascicles, and a whorled pattern. "Major cytokines, namely the expression of interleukin 1 (IL1), 6 (IL6), 11 (IL11), 13 (IL13), 15 (IL15), 33 (IL33), tumor necrosis factor α (TNFα), and the granulocyte-macrophage colony-stimulating factor, have been implicated to leiomyoma pathophysiology." (PMID 34442017, 2021). "Through ERK pathway, TNF-α promotes human leiomyoma smooth muscle cells migration and MMP-2 production." (PMID 41514933, 2026). "We sought to investigate the effect of STAT3, ERK, and AKT inhibitors in PCNA and TNF-α expression in leiomyoma cells cocultured with adipocytes and leptin treatment." (PMID 36771423, 2023). "The involvement of TNFα in leiomyoma cells’ differentiation and later proliferation has been especially thoroughly described." (PMID 34442017, 2021). "Although IL6, TNF-α, IFN-γ, G-CSF, and TGF-β1, which have been implicated in leiomyoma development, were expressed in both cell types, the most notable finding was the significantly different expression of Th2 and Th1/Th17 pathways in LPCs and MPCs." (PMID 29861738, 2018). "Another research indicated that the abundant expression of TNF-α might be a molecular basis characteristic of leiomyomas in the human uterus and that progesterone might play a vital role in down-regulating the expression of TNF-α in human uterine leiomyoma." (PMID 18274644, 2007). "Tumor necrosis factor-α (TNF-α) is higher in fibroid tissue compared to normal myometrium, thereby increasing Activin A expression in myometrial and leiomyoma cells, highlighting its importance in extracellular matrix (ECM) synthesis." (PMID 41514933, 2026). "Our study found that leptin treatment of leiomyoma cells increased pro-inflammatory factors, MCP-1, IFNγ, IL-8, GM-CSF, IL-6, and TNF-a." (PMID 36771423, 2023). "Leiomyoma cocultured with adipocytes and leptin treatment significantly increased in expression of PCNA and TNF-α." (PMID 36771423, 2023). "Leptin induces a tumor-friendly microenvironment through upregulation of pro-inflammatory (IFNγ, IL-8, IL-6, GM-CSF, MCP-1, and TNF-α), fibrotic (TGF-β1, TGF-β2, and TGF-β3), and angiogenic (VEGF-A, HGF, and Follistatin) factors in human leiomyoma cells." (PMID 36771423, 2023). "Finally, STAT3, ERK, and AKT inhibitor treatment suppressed PCNA, TNF-α, TGF-β3, and VEGF-A intracellular staining intensity in both adipocyte coculture and leptin treated leiomyoma cells." (PMID 36771423, 2023). "The respective inhibitors reduced the levels of pSTAT, pERK1/2, and pAKT and suppressed the intracellular staining intensity of PCNA, TNF-α, TGF-β3, and VEGF-A, in addition to reversing the effect of leptin treatment and adipocyte coculture on leiomyoma cell growth." (PMID 36771423, 2023). "Finally, increased levels of inflammatory cytokines, including interleukin (IL-1, IL-6) and tumor necrosis factor α (TNF-α), as well as increased numbers of reparative macrophages, were found to be present within leiomyoma." (PMID 37686792, 2023). "Importantly, in human leiomyomas, most of these signaling pathways, such as upregulation of mTOR, TGFB1 and CTNNB1 pathway, deregulation of IGF-1 signaling in human uterine leiomyoma and inflammatory process involving TNF signaling have been reported." (PMID 33244099, 2020). "Elevated IL-6/TNF-α occurred only in patients with EIN/EC (total of 23%), while no abnormalities were observed in the leiomyoma group." (PMID 41595367, 2026).
lumbar disc herniation (14 papers, 2009 to 2025). "Chronic low back pain associated with lumbar disk herniation may be related to inflammatory process and mediators such as tumor necrosis factor-alpha and serotonin which are released from mast cells and platelets as a consequence of tissue injury." (PMID 30327730, 2018). "Our team demonstrated that PMD occurs in patients with lumbar disc herniation, which is related to the high levels of TNF-α, IL-6, and IL-1β in multifidus." (PMID 40722201, 2025). "IVDs of patients with lumbar disc herniation have been shown to express proinflammatory cytokines, such as interleukin-1β (IL-1β) and tumor necrosis factor-α (TNF-α), which are known to stimulate the expression of ADAMTS in bovine cartilage." (PMID 19889209, 2009). "In addition, a previous study aimed at understanding the mechanism of EA in the treatment of patients with lumbar disc herniation, which is also a neuro edema disease, and found that EA can effectively reduce the levels of IL-2, TNF-α, and IL-6 contents." (PMID 38689877, 2024). "Elevated levels of phosphoLipids A2 (PLA2) and tumor necrosis factor (TNF), “key enzymes in the cascade of inflammation,” have been seen in lumbar disc herniations in symptomatic patients." (PMID 33240732, 2020). "LXA4 diminishes pain in the non-compressive lumbar disc herniation model by inhibiting production of pro-inflammatory cytokines (TNF-α, and IL-1β) and upregulating IL-10 and transforming growth factor-beta (TGF-β)." (PMID 37388729, 2023).
Lymphadenopathy (14 papers, 2008 to 2025). Enlargement (swelling) of a lymph node. "In HIV-infected individuals, EBV infection can cause atypical lymphoproliferation, lymphadenopathy, and lymphoid malignant transformations as an outcome of proinflammatory cytokine stimulation, such as tumor necrosis factor (TNF)." (PMID 33163531, 2020). "Fas mutation in MRL/MpJ mice significantly increased serum IL-6 and tumour necrosis factor-α (TNF-α) levels due to systemic autoimmunity and massive lymphadenopathy associated with the proliferation of aberrant T cells." (PMID 32686763, 2020). "Regarding the molecules secreted by these cells, IL-1β+ and TNF-α+ were found to be the most highly expressed, mainly in individuals with lymphadenopathy, followed by perforin+ and granzyme B+." (PMID 32766167, 2020). "Although some individuals had severe lymphadenopathy and necrosis that could be seen using imaging techniques, some of them had normal serum TNF-α values." (PMID 37007342, 2023). "Here IL-1β+ and TNF-α+ were both more frequent in patients with lymphadenopathy, and were positively correlated with granzyme expression, and necrosis was also strongly directly correlated with IL-1β+, which suggests that this cytokines plays a key role in the pathology of CL." (PMID 32766167, 2020). "The development of lymphadenopathy after combining anti-TNF and anti-CD11a therapy and the prompt resolution of symptoms after their discontinuation, followed by lack of recurrence with using anti-TNF therapy alone, suggests that these drugs caused or facilitated the development of this process." (PMID 18366773, 2008). "Similarly, IL-6 (P=0.0006), IL-10 (P=0.001), IL-12p40 (P=0.03), TNFα (P≤0.002) and chemokines MIP-1β (P<0.0001) and MCP-1 (P=0.002) (but not IL-1β, IL-13 and G-CSF) were significantly elevated in Tg mice at late stages of lymphadenopathy (Tg L) relative to WT controls." (PMID 23985023, 2013).
meningococcal disease (14 papers, 2005 to 2025). "Additionally, in vitro studies identified increased TNF-α concentrations in healthy carriers of at least one A allele after exposure to lipopolysaccharides or after meningococcal infection." (PMID 32171247, 2020). "Among these, the pro-inflammatory cytokines IL-6, which stimulates acute phase responses, haematopoiesis, and immune reactions, and TNF-α, a central early immune response activator, have both been related to meningococcal disease severity." (PMID 40818988, 2025). "The soluble cytokines investigated here included the instructive cytokines IL-6 and TNF, which are often described in the context of meningococcal infections and exposures." (PMID 38443838, 2024). "Meningococcal disease is hallmarked by elevated concentrations of proinflammatory cytokines and chemokines, including IL-1β, tumor necrosis factor (TNF), IL-6, and CXCL8 (formerly known as IL-8)." (PMID 31198794, 2019). "Lastly innate familial patterns of leukocyte TNFα and IL10 production have been linked with risk for mortality in meningococcal disease." (PMID 23935244, 2013). "Unstimulated primary endothelial cells do not express CEACAMs, but a strong upregulation of CEACAM1 is observed upon stimulation with pro-inflammatory cytokines such as TNFα, which is induced during meningococcal infection." (PMID 21298042, 2011). "This is in contrast to TNF-α, probably the most intensively studied cytokine in meningococcal disease, for which a cutoff value of 22.5 had a 78% sensitivity and 98% specificity." (PMID 16507164, 2006).
muscular atrophy (14 papers, 2010 to 2025). "In a previous study, we showed that immobilization-induced skeletal muscle atrophy is associated with the upregulation of the inflammation markers TNFα, IL-6, and IL-1." (PMID 21843349, 2011). "Systemic inflammation may trigger protein catabolism and impair the anabolic response whereby an increase in proinflammatory cytokines (e.g., TNF-α, IL-1, IL-6) is associated with muscular atrophy." (PMID 39497175, 2024). "Both TNF-α and IL-1beta have been associated with skeletal muscle atrophy." (PMID 24506836, 2014). "As an inflammatory factor, it is stated that TNF-α is necessary for cachexia-induced muscular atrophy." (PMID 39404384, 2024). "As a factor that promotes cachexia, miR-155 targets upstream genes of the TNF-α pathway to accelerate the procedure of muscular atrophy." (PMID 39404384, 2024). "Here, we demonstrate that PNF inhibits the progression of TNFα-induced skeletal muscle atrophy after menopause by restoring mitochondrial biosynthesis." (PMID 35455387, 2022). "Two main enzymes at the core of this system, the ubiquitin ligases muscle atrophy f-box (Atrogin1/MAFbx) and muscle ring finger-1 (MuRF1), increase significantly in muscular atrophy, in part due to enhanced expression of tumor necrosis factor alpha (TNF-α)." (PMID 25157231, 2014). "Third, we assumed that TNF-α contributes to muscular atrophy in critically ill patients by increasing protein degradation." (PMID 24651840, 2014). "The down-regulation of this important antioxidant in response to TNF-α treatment in our microarray data suggests a possible link between the regulation of Sod1 and TNF-induced muscular atrophy." (PMID 20967264, 2010). "Therefore, miR-29b targets PI3K and IGF-1 to promote various muscular atrophy in vivo and in vitro, such as in mouse models with cancer, aging, TNF-α, or denervation." (PMID 39404384, 2024). "Recently accumulated evidence indicates that a number of cytokines, most notably the pro-inflammatory cytokine, TNF-α, may promote muscular atrophy." (PMID 38892252, 2024). "Furthermore, Gm4117 contributes to mediating the TNF and FoxO expression in muscular atrophy, as the sponge of the miRNA-467/669 family." (PMID 39404384, 2024). "In the present study, we investigated for the first time whether quinic acid, a naturally occurring compound with known antioxidant and anti-inflammatory properties, can effectively attenuate skeletal muscle atrophy induced by immobilization stress in vivo and TNF-α-stimulated myotubes in vitro." (PMID 41299991, 2025). "It was found that functional electrical stimulation therapy and endurance exercise training can effectively reduce the level of TNF-α in SCI patients and animals, thus acting as a treatment against skeletal muscle atrophy." (PMID 36937344, 2023). "The activation of the FOXO family, which may be due to TNF-α, soluble TNF-like weak inducer of apoptosis (TWEAK), or IL-1, is common in skeletal muscle atrophy." (PMID 34724970, 2021). "It was found that the expression levels of TNF-α and TNF-α receptors were elevated in the atrophied skeletal muscle during the chronic phase of spinal cord injury patients, which played a very important role in mediating skeletal muscle atrophy during the chronic phase of SCI." (PMID 36937344, 2023).